MUSK (muscle associated receptor tyrosine kinase)
Diseases named in the same sentence as MUSK in open-access papers (continued):
Sharing a sentence is not in itself a finding about the gene and the disease.
myasthenia gravis (continued). "The symptoms of myasthenia gravis improved more in people with anti-MuSK antibodies who received rozanolixizumab than in those who received placebo." (PMID 39297052, 2024). "Approximately 5% of patients with myasthenia gravis can test positive for MuSK antibodies, which have a different pathogenesis compared to the most common AChR antibodies." (PMID 38911858, 2024). "Unexpectedly, Belimumab did not demonstrate significant efficacy in a phase II clinical trial for Myasthenia Gravis (AChR and MuSK) (ClinicalTrials.gov Identifier: NCT01480596)." (PMID 38698867, 2024). "MuSK is a tyrosine kinase involved in the transduction of electrical signals at the neuromuscular junction and is involved in MuSK myasthenia gravis (MG)." (PMID 38433835, 2024). "Myasthenia gravis (MG) is a rare autoimmune disorder in which antibodies block or destroy acetylcholine receptors, lipoprotein-related protein 4 or MuSK antigens in the postsynaptic membrane at the neuromuscular junction." (PMID 39666070, 2024). "We reported here chimeric antigen receptor (CAR) T cells targeting BCMA in two patients with highly relapsed and refractory myasthenia gravis (one with AChR-IgG, and one with MuSk-IgG)." (PMID 38409527, 2024). "The data from the autoimmune myasthenia gravis mouse model contributed to an investigational new drug application and phase 1 clinical study design for the treatment of MuSK autoantibody-positive myasthenia gravis." (PMID 39276207, 2024). "Muscle-specific kinase (MuSK)-myasthenia gravis (MuSK-MG) is a severe autoimmune disease of the neuromuscular junction (NMJ)." (PMID 38715598, 2024). "Preclinical and clinical studies have shown the efficacy of this approach in pemphigus vulgaris, MuSK autoantibody-positive myasthenia gravis, and NMDA receptor antibody encephalitis." (PMID 38673811, 2024). "Autoantibodies to muscle-specific kinase (MuSK) cause myasthenia gravis (MG)." (PMID 39288173, 2024). "This team has also recently applied the same principle to the treatment of muscle-specific tyrosine kinase myasthenia gravis (MuSK MG) for MuSK-specific B cell depletion." (PMID 39445021, 2024). "The prevalence of patients positive for muscle-specific kinase antibody (hereafter, MuSK-Ab) accounts for 5–8% of all myasthenia gravis (MG) cases." (PMID 39628891, 2024). "Preclinical studies on MuSK-CAART for myasthenia gravis treatment and desmoglein 3 (DSG3)-CAART for mucosal pemphigus vulgaris have shown that both CAARTs retained efficient levels of cytolysis activity in the presence of soluble antibodies." (PMID 38673811, 2024). "There are several reports of myasthenia gravis masquerading as ALS, especially in muscle-specific kinase (MuSK)-associated myasthenia." (PMID 37333000, 2023). "For example, Myasthenia gravis (MG), which is characterized by the production of antibodies that attach to muscle-specific kinase (MuSK), is distinguished by sporadic muscular stiffness with significant involvement of the axial and bulbar muscles." (PMID 37243095, 2023). "We immunized hIgG4-KI mice with OVA and recombinant human MuSK, as hIgG4-type anti-MuSK antibodies have been reported in myasthenia gravis." (PMID 36763580, 2023). "When the clinical suspicion of MG arises, anti-AChR antibodies are first tested, followed by Anti-MuSK in AChR-negatives, according to the Italian recommendations for the diagnosis and treatment of myasthenia gravis." (PMID 37510896, 2023). "Myasthenia gravis (MG) is caused by structural and functional changes in the postsynaptic membrane induced by autoantibodies against the acetylcholine receptor (AChR) or muscle-specific kinase (MuSK)." (PMID 37521306, 2023). "Myasthenia gravis (MG) is a prototypical autoimmune disease characterized by autoantibodies against acetylcholine receptor (AChR), muscle-specific tyrosine kinase (MuSK) or other postsynaptic muscle-associated proteins, and immunosuppressive therapies (ISTs) are inevitable for managing MG." (PMID 38375813, 2023).
myasthenia gravis (continued). "Muscle-specific kinase (MuSK) Myasthenia Gravis (MG) represents a prototypical antibody-mediated disease characterized by predominantly focal muscle weakness (neck, facial, and bulbar muscles) and fatigability." (PMID 37564637, 2023). "This developmental difference impacted disease severity in a model of MuSK-induced myasthenia gravis, in which NMJs of DeSyn muscles showed significantly decreased post-synaptic area compared to NMJs of FaSyn muscles." (PMID 35791011, 2022). "Since the first description of muscle-specific kinase antibody (MuSK-ab) as a novel autoantibody in 2001, MuSK antibody-associated myasthenia gravis (MuSK-MG) has been regarded as an MG subtype with unique molecular immunology underpinning the pathology and clinical characteristics." (PMID 34732168, 2021). "Here, we demonstrate that this process amplifies autoantibody pathogenicity in a classic IgG4-mediated autoimmune disease: muscle-specific kinase (MuSK) myasthenia gravis." (PMID 33753489, 2021). "Myasthenia gravis with antibodies (Abs) against the muscle-specific tyrosine kinase (MuSK) is a rare autoimmune disorder (AD) of the neuromuscular junction (NMJ) and represents a prototype of AD with proven IgG4-mediated pathogenicity." (PMID 34502051, 2021). "Muscle-specific tyrosine kinase (MuSK) myasthenia gravis (MG) is a rare, frequently more severe, subtype of MG with different pathogenesis, and peculiar clinical features." (PMID 32793097, 2020). "Here we demonstrate for the first time an attempt to modulate MuSK myasthenia gravis by feeding mice with low doses of recombinant MuSK." (PMID 32256489, 2020). "Compared to the more common myasthenia gravis with antibodies against the acetylcholine receptor (AChR), MuSK-MG affects mainly the bulbar and respiratory muscles, with more frequent and severe myasthenic crises." (PMID 32982689, 2020). "Patient-derived AChR, MuSK, and LRP4 autoantibodies in MG are demonstrably pathogenic (B cells in the pathophysiology of myasthenia gravis), and patients most often harbor only one of these autoantibody specificities." (PMID 33061827, 2020). "We utilized a recombinant MuSK protein for immunization and showed that 100% of mice developed MuSK myasthenia gravis, which was synchronously developed within a month after immunization." (PMID 32256489, 2020). "Myasthenia gravis (MG) is an autoimmune disorder caused by autoantibodies against the postsynaptic membrane at the neuromuscular junction, mostly against acetylcholine receptors (AChR) and in some against muscle-specific receptor tyrosine kinase (MuSK)." (PMID 31718587, 2019). "Moreover, autoantibodies to Agrin, Lrp4, or MuSK cause myasthenia gravis (MG), which is likewise distinct from ALS." (PMID 29460776, 2018). "Here, for the first time, we examined the potential benefit of albuterol in a mouse model of anti-Muscle Specific Kinase (MuSK) myasthenia gravis." (PMID 24505322, 2014). "Recent studies demonstrate reduced motor-nerve function during autoimmune muscle-specific tyrosine kinase (MuSK) myasthenia gravis (MG)." (PMID 25438154, 2014). "The results provide the first evidence that short-term albuterol treatment can ameliorate weakness in a robust mouse model of anti-MuSK myasthenia gravis." (PMID 24505322, 2014). "Muscle-specific tyrosine kinase- (MuSK-) antibodies-positive Myasthenia Gravis accounts for about one third of Seronegative Myasthenia Gravis and is clinically characterized by early onset of prominent bulbar, neck, shoulder girdle, and respiratory weakness." (PMID 21822490, 2011). "Myasthenia gravis is a rare auto-immune disorder characterized by the formation of antibodies against the nicotinic acetylcholine receptors at the neuromuscular junction or other postsynaptic muscle fibre components like muscle specific tyrosine kinase (MuSK)." (PMID 40656929, 2025).
myasthenia gravis (continued). "The myasthenia gravis (MG) subtypes acetylcholine receptor (AChR)-positive MG and muscle-specific kinase (MuSK)-positive MG provide an ideal model to explore atBCs due to the distinct immune mechanisms driven by IgG1-3 and IgG4 autoantibodies, respectively in the disease." (PMID 40607384, 2025). "In myasthenia gravis, clinical signs of cholinergic hyperactivity may point to seropositivity of MuSK antibodies with therapeutic implications in clinical practice." (PMID 40528144, 2025). "While nearly 90% of myasthenia gravis patients have autoantibodies targeting AChR and/or the muscle-specific tyrosine kinase (MuSK), other autoantibodies targeting striated muscles, particularly the sarcomere protein Titin, have been detected in some myasthenia gravis patients." (PMID 40625741, 2025). "Myasthenia gravis (MG) is a rare autoimmune disease characterized by the production of autoantibodies that target the nicotinic acetylcholine receptors (AChRs) or functionally related proteins (MuSK and LRP4), which disrupt neuromuscular transmission causing pronounced skeletal muscle weakness." (PMID 39657004, 2025). "Autoantibodies include long-lived antibodies against the acetylcholine receptor (AChR), mainly of the IgG1 subclass, and IgG4, produced almost exclusively by short-lived plasmablasts, which are prevalent in muscle-specific tyrosine kinase (MuSK) myasthenia gravis." (PMID 38881870, 2024). "Myasthenia gravis (MG) is a rare autoimmune disorder caused by specific antibodies against antigenic determinants of the neuromuscular junction, the main being nicotinic acetylcholine receptor (AChR), less frequently muscle‐specific tyrosine kinase (MuSK) or lipoprotein‐related protein 4 (LRP4)." (PMID 38164996, 2024). "To date, four preclinical studies have used CAART cell therapy for autoimmune disorders: specifically for the treatment of pemphigus vulgaris, MuSK autoantibody-positive myasthenia gravis, NMDAR encephalitis, and experimental autoimmune encephalomyelitis (EAE)." (PMID 38673811, 2024). "Myasthenia gravis (MG) is an autoimmune disorder characterized by autoantibodies against neuromuscular junctions, including anti‐acetylcholine receptor (AChR) and anti‐muscle‐specific tyrosine kinase (MuSK) antibodies." (PMID 38739094, 2024). "Myasthenia Gravis (MG) is a chronic autoimmune disease mediated by antibodies against the acetylcholine receptor (AChR), Muscle-Specific Kinase (MuSK) or other proteins in the neuromuscular junction such as Low-Density Lipoprotein Receptor Related Protein-4 (LRP4)." (PMID 37849836, 2023). "Myasthenia gravis (MG) is a neuromuscular disorder with antibodies directed against the skeletal muscle nicotinic acetylcholine receptor (AChR), the muscle specific kinase (MuSK)." (PMID 35802752, 2022). "Furthermore, RTX has been shown to decrease corticosteroid dependence, induce sustained remission, and have a favorable response to anti-MuSK antibody positive myasthenia gravis compared to anti-AChR antibody positive myasthenia gravis." (PMID 34909332, 2021). "However, new modalities of diagnosing myasthenia gravis were introduced such as the anti-MuSK and other autoantibodies tests." (PMID 35111450, 2021). "Auto-antibodies against MuSK and LRP4 cause Myasthenia gravis, whereas mutations affecting the function of each of these proteins are involved in Myasthenic Congenital Syndromes, thus demonstrating the requirement of these postsynaptic proteins for mature NMJ maintenance." (PMID 32848618, 2020). "However, his symptom of dysphagia was not explained by EDS, but was the early symptoms of muscle-specific kinase (MuSK) myasthenia gravis (MG) that we finally diagnosed later by progression of the symptoms and electrophysiologic study." (PMID 31355025, 2019). "The concept of epitope spreading has been reported in multiple sclerosis, AQP4 Ab in NMO, but not in MuSK Ab-associated myasthenia gravis, nor in 11 paediatric MOG Ab responses." (PMID 31481127, 2019).
myasthenia gravis (continued). "We present the case of a 73-year-old man with a medical history of myasthenia gravis and positive antibody titers against acetylcholine and anti-MuSK, who sought for medical assessment because of respiratory tract infection symptoms, dysphagia, and generalized weakness." (PMID 26783473, 2015). "Yet, electrical myotonia in myasthenia gravis associated with antibodies against muscle-specific tyrosine kinase (MuSK) has not been previously reported." (PMID 26770848, 2015). "Myasthenia gravis (MG) is an autoimmune disorder characterized by antibodies targeting acetylcholine receptors (AChR) or muscle-specific kinase (MuSK) at the neuromuscular junction, resulting in fluctuating skeletal muscle weakness." (PMID 42306025, 2026). "Myasthenia gravis (MG) with antibodies against MuSK-MG is a subtype of autoimmune neuromuscular junction disorder characterized by the presence of MuSK-Ab." (PMID 41476989, 2025). "In myasthenia gravis (MG) patients, the frequency of MuSK-IgG and AChR-IgG Fab N-glycosylation sites is elevated in the circulatory system compared to healthy individuals, though this does not affect their binding capacity." (PMID 41301426, 2025). "Myasthenia gravis (MG) is an autoimmune illness characterized by autoantibodies against the acetylcholine receptor (AChR), muscle-specific tyrosine kinase (MuSK), and an increasing number of extra postsynaptic proteins." (PMID 38803727, 2024). "The discovery of autoantibodies directed against muscle-specific kinase (MuSK) in “seronegative” myasthenia gravis (MG) patients marked a milestone in MG research." (PMID 39703505, 2024). "Muscle-specific tyrosine kinase (MuSK) antibody-positive myasthenia gravis (MG) is a rare but more severe subtype of MG that occurs acutely and affects mainly the bulbar and facial muscles." (PMID 38975540, 2024). "Myasthenia gravis (MG) is an autoimmune disorder characterized by muscle weakness and fatigue that primarily affects the neuromuscular junction through the production of autoantibodies against acetylcholine receptor antibodies (AChR-Abs) and muscle-specific kinase antibodies (MuSK-Abs)." (PMID 39273817, 2024). "Increasing data are available on the use and efficacy of rituximab (RTX) in patients with anti-muscle-specific tyrosine kinase (MuSK)-positive myasthenia gravis (MG), especially those steroid-dependent or unresponsive to traditional immunotherapies." (PMID 39088160, 2024). "Muscle-specific kinase (MuSK) myasthenia gravis (MG) is relatively rare and has a higher incidence of myasthenic crisis compared with other subtypes." (PMID 39624088, 2024). "Autoimmune myasthenia gravis (MG) also compromises the NMJ signal transduction but is caused by autoantibodies against the acetylcholine receptor (AChR), muscle-specific receptor tyrosine kinase (MuSK), low-density lipoprotein receptor-related protein 4 (LRP4), or others." (PMID 36835142, 2023). "In patients with neuromuscular disorders, eight patients had myasthenia gravis (MG) and one muscle-specific tyrosine kinase (MuSK) MG." (PMID 38288171, 2023). "Myasthenia gravis (MG) is an autoimmune disease caused by pathogenic autoantibodies targeting the neuromuscular junction (NMJ); these include anti-acetylcholinereceptor (AchR), anti–muscle-specific tyrosine kinase (MuSK), and anti–low-density lipoprotein receptorrelated protein 4 (LRP4) antibodies." (PMID 35873770, 2022). "Anti-muscle-specific kinase (MuSK) positive myasthenia gravis (MG) is characterized by a high relapsing rate, thus, choosing the appropriate oral drug regimen is a challenge." (PMID 35775051, 2022). "Acetylcholine receptor antibodies (AChR), muscle-specific kinase (MuSK), and lipoprotein-associated protein (LRP4) have been well established as sensitive diagnostic markers and pathogens, in addition to antibodies in the classification of patients with Myasthenia gravis also play a key role." (PMID 34930325, 2021).
myasthenia gravis (continued). "Myasthenia gravis (MG) with antibodies against muscle-specific kinase (MuSK) is one of the first recognized IgG4-mediated autoimmune diseases." (PMID 33753489, 2021). "Myasthenia gravis (MG) is a chronic, immune-related neuromuscular disease with presence of autoantibodies against nicotinic acetylocholine receptors (AChR), muscle-specific kinase (MuSK) autoantibodies to low-density lipoprotein receptor-related protein 4 (Lpr4) or remains seronegative." (PMID 34502425, 2021). "The concomitance between Parkinson's disease (PD) and myasthenia gravis (MG) is rare, with only a few case reports in the literature and only one of them with positive anti-muscle specific kinase (anti-MuSK) MG." (PMID 34104586, 2021). "But around 10-20% of patients with myasthenia gravis are found to be seronegative for AChR antibodies, and antibodies to the muscle-specific tyrosine kinase (MuSK) are found in 0-70% of MG patients." (PMID 34909332, 2021). "Myasthenia gravis (MG) with antibodies to the muscle-specific receptor tyrosine kinase (MuSK) is a distinct sub-group of MG, affecting 5–8% of all MG patients." (PMID 32256489, 2020). "Myasthenia gravis (MG) is an organ-specific rare autoimmune disorder of neuromuscular junction where auto-antibodies are directed to the nicotinic acetylcholine receptor (nACHR), the muscle-specific tyrosine kinase (MuSK) or lipoprotein receptor-related protein 4 (LRP4)." (PMID 32642338, 2020). "The onset of myasthenia gravis with anti-muscle-specific tyrosine kinase antibodies (MuSK-MG) most commonly peaks in the late 30s, and an onset at a later age is unusual." (PMID 32532281, 2020). "Autoimmune myasthenia gravis (MG) is a neuromuscular junction disorder marked clinically by fatigable muscle weakness and serologically by the presence of autoantibodies against acetylcholine receptors (AChRs), muscle-specific kinase (MuSK), or lipoprotein-related protein 4 (LPR4)." (PMID 30443340, 2018). "Myasthenia gravis (MG) is an autoimmune disease in which 90% of patients have autoantibodies against the muscle nicotinic acetylcholine receptor (AChR), while autoantibodies to muscle-specific tyrosine kinase (MuSK) have been detected in half (5%) of the remaining 10%." (PMID 26284792, 2015). "We investigated the influence of postsynaptic tyrosine kinase signaling in a mouse model of muscle‐specific kinase (MuSK) myasthenia gravis (MG)." (PMID 26702075, 2015). "Neuromuscular transmission failure in myasthenia gravis (MG) is most commonly elicited by autoantibodies (ab) to the acetylcholine receptor or the muscle-specific kinase, constituting AChR-MG and MuSK-MG." (PMID 25893403, 2015). "A variable proportion of patients with generalized myasthenia gravis (MG) have autoantibodies to muscle specific tyrosine kinase (MuSK)." (PMID 24244707, 2013). "Myasthenia gravis (MG) is a prevalent autoimmune disorder affecting neuromuscular junctions, typically characterized by muscle weakness due to autoantibodies targeting acetylcholine receptors (AChR) or muscle-specific kinase (MuSK)." (PMID 41897632, 2026). "However, emerging case reports have documented efgartigimod’s off-label use in diverse MG presentations, including MG patients with positive MuSK antibodies, refractory MG, and ocular myasthenia gravis." (PMID 41159035, 2025). "CNS: central nervous system; EMG: electromyography; NCS: nerve conduction study; CSF: cerebrospinal fluid; IVIG: IV immunoglobulin; MG: myasthenia gravis; LEMS: Lambert-Eaton myasthenic syndrome; AchR: acetylcholine receptor; MuSK: muscle-specific kinase." (PMID 40151710, 2025). "Double Seropositive Myasthenia Gravis (DSP-MG) is a rare subtype of Myasthenia Gravis (MG) characterized by the simultaneous presence of anti-acetylcholine receptor (AChR) antibodies and muscle-specific tyrosine kinase (MuSK) antibodies." (PMID 41159035, 2025).